ARHGEF38 (Rho guanine nucleotide exchange factor 38)
Description:
May act as a guanine-nucleotide releasing factor.
Synonyms: FLJ20184
Tractability: No criterion of Open Targets' tractability assessment is met for any kind of drug.
Gene: Protein-coding gene on chromosome 4 (105,552,620 to 105,708,093, forward strand). Ensembl gene ENSG00000236699.
Subcellular location (Human Protein Atlas): Nucleoplasm; Centrosome
Pathways (Reactome):
Signal Transduction: G alpha (12/13) signalling events; NRAGE signals death through JNK
Gene Ontology:
Molecular function: guanyl-nucleotide exchange factor activity
Cellular component: cytoplasm
Genetic constraint (gnomAD): Loss-of-function variants: 75 observed, 75.09 expected, observed/expected ratio (o/e) 1, 90% interval 0.83 to 1.21. The upper end of that interval is the gene's LOEUF score, 1.21, which puts it in group 5 of 6, group 1 being the genes least tolerant of losing a copy. Missense variants: 914 observed, 901.7 expected, observed/expected ratio (o/e) 1.01, 90% interval 0.96 to 1.07. Synonymous variants: 346 observed, 328.46 expected, observed/expected ratio (o/e) 1.05, 90% interval 0.96 to 1.15.
Homologues: Orthologues: macaque ARHGEF38 (98% identical), rabbit ARHGEF38 (89% identical), pig ARHGEF38 (88% identical), dog ARHGEF38 (87% identical), rat Arhgef38 (85% identical), mouse Arhgef38 (84% identical), chimpanzee ARHGEF38 (66% identical), tropical clawed frog arhgef38 (64% identical), zebrafish arhgef38 (52% identical), Caenorhabditis elegans dnbp-1 (23% identical). Paralogues in human: DNMBP (41% identical), ARHGEF37 (25% identical).
Diseases named in the same sentence as ARHGEF38 in open-access papers:
ARHGEF38 is named in the same sentence as 13 diseases in open-access papers, as found by Europe PMC text mining. Sharing a sentence is not in itself a finding about the gene and the disease. The quoted sentences say what the papers report.
bipolar disorder (3 papers, 2020 to 2023). A disorder of the brain that causes unusual shifts in mood, energy, activity levels and the ability to carry out day-to-day tasks. "An examination in the prefrontal cortex (BA 46) of ARHGEF38 (rho guanine nucleotide exchange factor 38) in (N = 23) suicide completers diagnosed with a form of bipolar disorder by the DSM-IV criteria demonstrated hypomethylation across four CpG sites." (PMID 37174656, 2023). "Among possible targets of these eRNA candidates are ARHGEF38 and SH3YL1, which have been linked to bipolar disorder and suicide, GLRA1 and MCTP2 were found to be associated with schizophrenia, and CHIR-B3, MHCIA7, MHCIY as well as MICA are genes involved in the immune system." (PMID 32854615, 2020). "However, a recent study has related alterations in the methylation pattern of the Arhgef38 gene to changes in several pathways including axonal guidance signaling, calcium signaling, β-adrenergic signaling, and opioid signaling, in individuals with bipolar disorder." (PMID 32168507, 2020).
prostate carcinoma (3 papers, 2021 to 2025). A carcinoma that arises from epithelial cells of the prostate gland. "Our study reveals that SLC14A1, ARHGEF38, NEFH, MSMB, KRT23, and KRT15 are potential diagnostic biomarkers for prostate cancer, among which MSMB may play a protective role in prostate cancer." (PMID 40260298, 2025).
epilepsy (1 paper, 2020). A brain disorder characterized by episodes of abnormally increased neuronal discharge resulting in transient episodes of sensory or motor neurological dysfunction, or psychic dysfunction. "Our study nevertheless identifies high-impact variations in the Asb14, Msh3 and Arhgef38 genes, with important functional consequences in the resulting proteins, albeit with no known relationship with any type of epilepsy." (PMID 32168507, 2020). "Protein analysis of the other two genes with high- impact variants, Asb14 and Arhgef38, also predicts changes in their function, yet neither ASB14 (ankyrin repeat and SOCS box containing 14) nor ARHGEF38 have been associated with any type or case of epilepsy." (PMID 32168507, 2020).
nasopharyngeal carcinoma (1 paper, 2022). A carcinoma arising from the nasopharyngeal epithelium. "Dysregulated expression of ARHGEF38 is associated with poor prognosis in nasopharyngeal carcinoma." (PMID 35372462, 2022).
prostate tumors (1 paper, 2021). "Compared to normal tissues, ARHGEF38, NETO2, GOLM1, and SAPCD2 were hypomethylated in prostate tumors, while PRSS21 was hypermethylated in prostate tumors compared, which may be the underlying mechanism for the abnormal expression of the five genes in PCa." (PMID 34540835, 2021).
tumor (2 papers, 2022 to 2025). "Conversely, the upregulation of ARHGEF38, a gene implicated in cell signaling and cytoskeletal reorganization, suggests its potential involvement in promoting tumor growth and metastasis." (PMID 40260298, 2025). "A three-gene signature model (KCNK3, AK5, and ARHGEF38) was established, and the model was significantly associated with cancer-related pathways, overall survival (OS), and tumor microenvironment (TME)-related immune cells in PCa." (PMID 35372462, 2022). "The results demonstrated that ARHGEF38 protein expression was significantly elevated in tumor tissues." (PMID 40260298, 2025). "IHC results confirmed that ARHGEF38 protein was highly expressed in tumor tissues, while MSMB expression was markedly reduced." (PMID 40260298, 2025). "The IHC results revealed that ARHGEF38 protein was highly expressed in tumor tissues, while MSMB exhibited reduced expression in tumor tissues compared to para-cancerous tissues." (PMID 40260298, 2025). "The IHC results confirmed that ARHGEF38 protein was highly expressed in tumor tissues, while MSMB expression was markedly reduced, consistent with the qRT-PCR and Western blot data." (PMID 40260298, 2025). "Our results revealed that, compared to para-cancerous tissues, the expression levels of SLC14A1, NEFH, MSMB, KRT23, and KRT15 were significantly downregulated in PCa tumor tissues, while ARHGEF38 expression was notably upregulated, consistent with our initial predictions." (PMID 40260298, 2025).
cancer (1 paper, 2022). A tumor composed of atypical neoplastic, often pleomorphic cells that invade other tissues. "A three-gene signature model (KCNK3, AK5, and ARHGEF38) was constructed, and the model was significantly related to cancer-related pathways, overall survival, and TME cells in PCa." (PMID 35372462, 2022).
ARHGEF38 also shares sentences with these, for which no sentence is quoted: benign prostate hyperplasia (1 paper); breast cancer (1); infection (1); infective endocarditis (1); lymph node metastasis (1); schizophrenia (1).